CLDN5 (claudin 5)
Diseases named in the same sentence as CLDN5 in open-access papers (continued):
Sharing a sentence is not in itself a finding about the gene and the disease.
influenza (5 papers, 2012 to 2023). An acute viral infection of the respiratory tract, occurring in isolated cases, in epidemics, or in pandemics; it is caused by serologically different strains of viruses (influenzaviruses) designated A, B, and C, has a 3-day incubation period, and usually lasts for 3 to 10 days. "Replication-deficient influenza caused a significant and dose-dependent reduction in claudin-5 levels in the endothelial monolayer, as assessed by both immunofluorescence and immunoblotting." (PMID 23115643, 2012). "Loss of claudin-5 was required for the observed increase of permeability, as over-expression of claudin-5 or treatment with formoterol, a compound that induces claudin-5 expression, was sufficient to prevent replication-deficient influenza induced endothelial leak." (PMID 33499234, 2021). "Furthermore, formoterol attenuated the loss of claudin-5 provoked by replication-deficient influenza, leading to enhanced protein expression at the cell membrane and in intracellular organelles." (PMID 23115643, 2012). "Thus, over-expression of claudin-5 is sufficient to block replication-deficient influenza-induced leak." (PMID 23115643, 2012). "We have previously reported that claudin-5 expression is decreased in cultured lung endothelial cells exposed to human influenza; here we found that mice infected with influenza also show decreased expression of claudin-5 in lung homogenates." (PMID 37310768, 2023). "Instead, our data suggest that influenza induces endothelial permeability by stimulating the degradation of claudin-5 from the cell surface by matrix metalloproteases." (PMID 23115643, 2012). "In addition, claudin 5 is a primary tight junction component expressed in pulmonary endothelial cells and has been shown to be downregulated in the lungs during influenza infection and other models of ALI." (PMID 35111077, 2021). "Claudin-5 is the predominant tight junction molecule expressed in pulmonary endothelial cells and has been found to be downregulated in various models of ALI, such as influenza infection." (PMID 35111077, 2021). "It has been reported that apoptosis, degradation of the tight junction protein claudin-5 (Claudin-5), virus–cytokine-protease cycle, and phosphorylation of myosin light chain (MLC) may play certain roles in influenza–induced endothelial leak." (PMID 29059211, 2017).
viral infection (5 papers, 2012 to 2025). "In other infection models, such as infection with Group B Streptococcus, CNS tuberculosis, or viral infections of the CNS, the importance of claudin-5 for the course of infection and bacterial passage through the BBB was also demonstrated." (PMID 39768195, 2024). "In principle, the decrease in claudin-5 protein after viral infection could represent an impairment of protein synthesis and/or an increase in its degradation." (PMID 23115643, 2012). "In viral infection, brain microvascular endothelial cells exposed to the human immunodeficiency virus-1 (HIV-1) Tat protein decreased expression of claudin-5 and induced a redistribution of claudin-5 from cell-cell borders." (PMID 23505411, 2013). "Similarly, while a role for the ubiquitin-proteasome system in claudin-5 metabolism was recently reported, we detected no increase in ubiquitination of the protein after viral infection." (PMID 23115643, 2012).
bipolar disorder (4 papers, 2020 to 2024). A disorder of the brain that causes unusual shifts in mood, energy, activity levels and the ability to carry out day-to-day tasks. "We also found that reduced levels of claudin-5 were associated with increased duration of bipolar disorder." (PMID 33139732, 2020). "Also in mental disorders such as ASD, ADHD and bipolar disorder, increased serum zonulin and/or claudin-5 levels are observed which is associated with respectively increased intestinal and BBB permeability." (PMID 34021199, 2021). "While we did not have clinical measurement of cognitive function in our study, we did find consistent associations between the age of onset of illness and the levels of claudin-5 with earlier onset of bipolar disorder associated with reduced levels of claudin-5." (PMID 33139732, 2020). "Levels of claudin-5 negatively correlated with the duration of bipolar disorder in the orbitofrontal white matter (r = −0.5135, P = 0.0522) and orbitofrontal grey matter (r = −0.7067, **P = 0.0042)." (PMID 33139732, 2020). "Levels of claudin-5 positively correlated with the age of onset of bipolar disorder in the hippocampus white matter (r = 0.6442, P = 0.044 (not significant with FDR correction)), grey matter (r = 0.586, *P = 0.030) and orbitofrontal white matter (r = 0.6172, *P = 0.0162)." (PMID 33139732, 2020).
diabetic nephropathy (4 papers, 2017 to 2025). "A recent study reported that KO mice lacking the podocyte-specific tight junction integral membrane protein claudin-5 exhibit podocyte injury and proteinuria with diabetic nephropathy." (PMID 39101921, 2024). "Using podocyte-specific Cldn5 knockout mice, we identify CLDN5 as a crucial regulator of podocyte function and reveal that Cldn5 deletion exacerbates podocyte injury and proteinuria in a diabetic nephropathy mouse model." (PMID 35332151, 2022).
heart failure (4 papers, 2016 to 2026). Inability of the heart to pump blood at an adequate rate to meet tissue metabolic requirements. "Decreased Claudin-5 levels were independent and much more common than changes in other cell junctions and membrane-associated proteins known to be involved in human heart failure, including Cx-43 and dystrophin." (PMID 36408244, 2022). "We have previously demonstrated that claudin-5 protein is reduced in the majority of end-stage human heart failure samples." (PMID 27999547, 2016).
Hypoglycemia (4 papers, 2014 to 2024). A decreased concentration of glucose in the blood. "However, AQP4 deletion preserved the loss of claudin-5 caused by hypoglycemia (#p < 0.05 vs. Hypo group)." (PMID 29793504, 2018). "Interestingly, VE-cadherin was shown to positively regulate the transcription of claudin-5, thus providing an alternative explanation for loss of claudin-5 by hypoglycemia." (PMID 24708805, 2014). "Here, in order to investigate the role of AQP4 deficiency in hypoglycemia-induced degradation of BBB components, we analyzed the expression of claudin-5, a major tight junction protein, and AQP4 via Western blot." (PMID 29793504, 2018). "We previously demonstrated that the breakdown of the BBB was attributed to the degradation of claudin-5 in early critical events in acute severe hypoglycemia, which result in edema formation." (PMID 29793504, 2018). "It was previously shown that increased AQP4 and degradation of claudin-5 were involved in acute hypoglycemia-induced brain edema both in vivo and in vitro." (PMID 29793504, 2018). "Western blot analysis revealed that hypoglycemia induced a time- and glucose dose-dependent decrease in claudin-5 protein levels." (PMID 25761767, 2015). "In summary, the present study demonstrated that hypoglycemia disrupts the BBB by reducing claudin-5 expression and increasing endothelial cell death, thereby increasing endothelial permeability." (PMID 25761767, 2015). "Taken together, hypoglycemia can significantly increase paraendocellular permeability by downregulating claudin-5 expression." (PMID 25761767, 2015). "Interestingly, hypoglycemia-induced claudin-5 downregulation was alleviated in the AQP4−/− + Hypo mice." (PMID 29793504, 2018). "The Western blot results showed that claudin-5 expression was downregulated after hypoglycemia." (PMID 29793504, 2018). "Furthermore, immunofluorescence staining for AQP4 (green) and claudin-5 (red) was performed in the cortex of the brain after hypoglycemia in mice." (PMID 29793504, 2018). "Confocal microscopy analysis showed that claudin-5-positive staining was continuously located on the endothelial cell margin of the cerebral microvessels in the WT mice; this continuity was disrupted by hypoglycemia." (PMID 29793504, 2018). "Moreover, the hypoglycemic medium in presence of VEGF decreased endothelial permeability via the inhibition of claudin-5 degradation and improved hypoglycemia-induced cell toxicity." (PMID 25761767, 2015). "The potential mechanisms regulating the change in claudin-5 expression is still unclear, although we speculate that it is related to glucose depletion during hypoglycemia." (PMID 25761767, 2015). "Our findings suggest that VEGF may prevent BBB disruption during hypoglycemia by inhibiting the degradation of claudin-5." (PMID 25761767, 2015). "Therefore, in this study, we attempt to investigate whether hypoglycemia induces cerebral endothelial dysfunction by regulating claudin-5, occluding and ZO-1." (PMID 25761767, 2015). "Our data indicated that hypoglycemia disrupted claudin-5 expression, without affecting the translocation of claudin-5, and increased paraendothelial permeability." (PMID 25761767, 2015). "The results clearly showed that hypoglycemia significantly downregulated the expression of claudin-5 in bEnd.3 cells, without affecting ZO-1 and occludin expression and distribution." (PMID 25761767, 2015).
pancreatic cancer (4 papers, 2008 to 2025). "Methylation of CLDN4 and CLDN5 has been reported in bladder and pancreatic cancer, respectively." (PMID 26198249, 2015). "These genes include UCHL1 (methylated in 100% of 42 pancreatic cancers), NPTX2 (98%), SARP2 (95%), CLDN5 (93%), reprimo (86%), LHX1 (76%), WNT7A (71%), FOXE1 (69%), TJP2 (64%), CDH3 (19%), and ST14 (10%)." (PMID 19424480, 2008).
prostate carcinoma (4 papers, 2012 to 2019). A carcinoma that arises from epithelial cells of the prostate gland. "CLDN1 and CLDN5 are down-regulated in many cancers and also in mesotheliomas and low expression of these claudins are associated with more aggressive prostate cancer." (PMID 22905093, 2012). "Nevertheless, this study demonstrates for the first time that Akt1 suppression in endothelial cells will promote prostate cancer metastasis involving β-catenin-mediated suppression of tight-junction proteins such as claudin-5, ZO-1 and ZO-2." (PMID 29755115, 2018). "Interestingly, reduced expression of claudin-5, ZO-1 and ZO-2 in the shAkt1 HLECs was rescued upon treatment with β-catenin inhibitors ICG001 and IWR-1, which resulted in the attenuation of DU145 prostate cancer cell invasion through shAkt1, compared to a shControl HLEC monolayer in vitro." (PMID 29755115, 2018).
psychosis (4 papers, 2018 to 2024). "Claudin-5 has been linked to mental illnesses such as personality disorders as bipolar disorder, psychosis, and obsessive compulsive disorder." (PMID 39592970, 2024). "We next investigated associations between some of the common features of psychiatric disorders with levels of claudin-5 protein; including incidence of psychosis and suicide." (PMID 33139732, 2020). "Also, two recent investigations found lower claudin-5 levels among individuals with mood disorders and psychosis." (PMID 39592970, 2024). "Interestingly, reduced claudin-5 in mice induces psychosis-like behaviors." (PMID 33133060, 2020).
angiosarcoma (3 papers, 2018 to 2024). A malignant tumor arising from the endothelial cells of the blood vessels. "Claudin 5 is a transcriptional target of FoxO1 and a marker of angiosarcoma cells within transformed lesions." (PMID 30559384, 2018). "Claudin-5 (CLDN5) has been found to be expressed in angiosarcomas and benign vascular tumors." (PMID 38540693, 2024).
atherosclerosis (3 papers, 2020 to 2024). A disease characterized by the build-up of fatty material and calcium deposition in the arterial wall resulting in partial or complete occlusion of the arterial lumen. "Higher endothelial permeability is a characteristic of atherosclerosis-susceptible arterial sites, which also tend to have reduced expression of claudin-5." (PMID 39201392, 2024). "The expression levels of claudin-5, ZO-1, and occludin are decreased in the cerebral microvessels of mice fed a high-fat diet, indicating that the combined effects of diet and cadmium exposure accelerate the development and progression of atherosclerosis." (PMID 39456818, 2024).
brain hemorrhage (3 papers, 2018 to 2025). "In intracranial hemorrhage, claudin-5, occludin, and ZO-1 sampled from cerebrospinal fluid may be more specific than serum markers." (PMID 30259344, 2018). "Thus, claudin-5 plays an important role in the barrier properties of the BBB, and the lack of adverse effects such as brain hemorrhage, edema, and behavioral changes due to transient claudin-5 knockdown is important and advantageous from the perspective of drug delivery to the brain." (PMID 33352631, 2020).
colon cancer (3 papers, 2022 to 2023). "CMS4 was characterized by suppression of claudin 2, claudin 3, claudin 7, and occludin and upregulation of claudin 5 mRNAs, not aligning with any of the three TCGA genomic groups or with CMS2 despite the similarities in the prevalence of common colon cancer mutations." (PMID 37998722, 2023).
colorectal cancer (3 papers, 2005 to 2026). A primary or metastatic malignant neoplasm that affects the colon or rectum. "Our findings revealed that the mRNA expression levels of CLDN1, CLDN2, CLDN12, and CLDN14 were upregulated in colorectal cancer tissues relative to normal tissues in the Oncomine database, whereas CLDN3, CLDN5, CLDN7, CLDN8, CLDN11, CLDN15, and CLDN23 were downregulated, as previously reported." (PMID 35281827, 2022).
diabetic retinopathy (3 papers, 2020 to 2023). "MMP-9 is known to degrade occludin and claudin-5 in focal cerebral ischemia, and it has been reported that it affects the expression of occludin, claudin-5, and ZO-1 and ZO-2 levels in early diabetic retinopathy." (PMID 32178308, 2020). "VME treatment reduced specific indicators of diabetic retinopathy, such as the degradation of OCLN (occludin), ZO-1 (zonula occludens-1), CLDN5 (claudin-5), and VEGF (retinal vascular endothelial growth factor) expression in diabetic rats." (PMID 37836403, 2023).
esophageal cancer (3 papers, 2016 to 2023). A primary or metastatic malignant neoplasm involving the esophagus. "Interestingly, our analysis revealed higher CLDN5 expression in primary esophageal cancer tissue compared to adjacent normal tissue, indicative of its potential significance in ESCC." (PMID 37303041, 2023). "However, CLDN5 has been described as an oncogene in breast, pancreatic, and esophageal cancers." (PMID 32156068, 2020). "Claudin-5 expression is revealed to correlated with lymph node metastasis in esophageal carcinoma which is not shown in our study." (PMID 27398181, 2016).
gastric cancer (3 papers, 2023). A primary or metastatic malignant neoplasm involving the stomach. "Based on the ROC curve analysis, CLDN5 demonstrates outstanding diagnostic effectiveness for gastric cancer and is comparable to CA-199." (PMID 37286335, 2023). "Further we found that CLDN5 was associated with gastric cancer and immune infiltration by MSI and TMB, methylation enzymes as well as immune infiltration analysis and immune checkpoint analysis." (PMID 37286335, 2023). "The findings were statistically significant and corroborated the findings of TCGA, indicating elevated CLDN5 was associated with lymph node metastasis in patients with gastric cancer, with clinical staging being lymph node metastasis." (PMID 37286335, 2023). "Recent research suggested that CLDN5 frameshift mutations in TJ and gap junction genes may cause gastric cancer." (PMID 37286335, 2023). "For predicting gastric cancer and immunotherapy, CLDN5 was found to be a promising biomarker of STAD." (PMID 37286335, 2023). "Immunohistochemistry was used to assess CLDN5 staining in gastric cancer tissues and paracancerous tissues." (PMID 37286335, 2023). "Meanwhile, CLDN5 expression in several datasets was validated, and ROC curves in TCGA training and the GEO test set were assessed, suggesting an effective role for CLDN5 in the diagnosis of gastric cancer." (PMID 37286335, 2023). "From this study, CLDN5 was found to be a promising biomarker of gastric cancer." (PMID 37286335, 2023). "Finally we verified that CLDN5 is reduced in gastric cancer by multiple datasets and tissue microarrays, and our results suggest that CLDN5 is a promising molecule for the early diagnosis and treatment of gastric cancer." (PMID 37286335, 2023). "C11_VWF were characterized by co‐expressing marker genes of fibroblasts (COL1A1, FAP, VIM, ACTA2) and endothelial cells (VWF, PECAM1, CLDN5, FLT1, RAMP2), which resembled a subgroup of cells undergoing an EMT transition in gastric cancer." (PMID 38115703, 2023).
glomerular disease (3 papers, 2021 to 2025). "Using super-resolution 3D-SIM we have previously shown that slit diaphragm components, such as CLDN5, can change their localization in case of glomerulopathy." (PMID 40563084, 2025). "In conclusion, our study showed CLDN5 localization to effaced areas of the FS in human and mouse glomerulopathies." (PMID 34156149, 2021). "CLDN5/nephrin ratios in human glomerulopathies and NTS‐treated mice were significantly higher compared to controls." (PMID 34156149, 2021). "To determine whether CLDN5 expression is also altered in human glomerular diseases, we queried the published transcriptomic datasets in kidney disease compiled in the Nephroseq database (nephroseq.org)." (PMID 35332151, 2022).
HIV-1 infection (3 papers, 2016 to 2021). The type species of lentivirus and the etiologic agent of acquired immunodeficiency syndrome (AIDS). "HIV-1 infection is associated with disrupted claudin-5 and occludin integrity which correlate with monocyte infiltration of the CNS." (PMID 30691500, 2019). "Data normalized to samples’ actin levels showed that compared to the control PBS group, HIV-1 infection decreased the expression of claudin-5, ZO-1, and ZO-2, respectively, by 3.8-fold (P = 0.03), 6.7-fold (P = 0.0005) and 4.85-fold (P = 0.006)." (PMID 34809709, 2021). "In humanised mice, HIV-1 infection is associated with impaired SHH signalling, downregulated expression of claudin-5 and leakage of Evans’ blue dye while an agonist to smoothened rescues this loss." (PMID 30691500, 2019). "Metamorph quantification of TJ proteins expression in all animals (9 to 11 mice in each group) showed that HIV-1 infection decreased claudin-5 expression by 5.2-fold (P < 0.0001) and decreased ZO-1 and ZO-2 expression by 3-fold (P < 0.0001) compared to PBS control." (PMID 34809709, 2021).
inflammatory bowel disease (3 papers, 2020 to 2025). A spectrum of small and large bowel inflammatory diseases of unknown etiology. "IL-21 may trigger gut inflammation and plays a role in inflammatory bowel disease, while claudin-5 is a downstream gene of this cytokine." (PMID 36256663, 2022).
injury (3 papers, 2018 to 2022). Damage inflicted on the body as the direct or indirect result of an external force, with or without disruption of structural continuity. "In this study, we found that ADSC-sEVs protect against LPS-induced pulmonary microvascular barrier damage and acute lung injury by alleviating apoptosis and reducing the loss of the tight junction-related proteins ZO-1 and claudin-5." (PMID 35681240, 2022). "A previous study has shown that following traumatic brain injury, the expression of N-cadherin, Cx43, and tight junction proteins, such as claudin-5, ZO-1, and JAM-a, was downregulated." (PMID 36262250, 2022).
intracerebral hemorrhage (3 papers, 2022 to 2025). A cerebrovascular disorder characterized by bleeding into one or both cerebral hemispheres including the basal ganglia and the cerebral cortex. "To test the possibility that inherent alterations in platelet aggregation may contribute to increased intracerebral hemorrhage in PAR4-/- mice, we examined CD41/Claudin-5 double-immunostaining in the perilesional cortex at 24 hours after TBI." (PMID 41438023, 2025).